CRP (C-reactive protein)
Diseases named in the same sentence as CRP in open-access papers (continued):
Sharing a sentence is not in itself a finding about the gene and the disease.
endothelial dysfunction (continued). "Recently, studies have focused on inflammatory biomarkers and risk factors for endothelial dysfunction, such as C-reactive protein (CRP), and tumor necrosis factor-α (TNF-α) that are considered to be prognostic factors for the development of DR." (PMID 33790859, 2021). "In animal models, overexpressing CRP has caused elevated SBP, likely due to CRP-induced endothelial dysfunction and oxidative stress, which further supports a causal interpretation of the effect of CRP on elevated BP." (PMID 34943129, 2021). "CRP has also been associated with endothelial dysfunction, exhibited as diminished large artery compliance in AA but not in CA." (PMID 34899053, 2021). "In conclusion, together with CRP, galectin-3 was independently associated with endothelial dysfunction in patients with CKD." (PMID 34437403, 2021). "It has been reported that android body fat is strongly associated with circulating levels of CRP and fibrinogen, thus increasing the risk of subclinical inflammation, leading to endothelial dysfunction." (PMID 34956040, 2021). "Specifically, endothelial dysfunction leads to the elevation of various cytokines, and CRP, predisposing individuals toward a proinflammatory, and prothrombotic state, and putting them at higher risks for perioperative complications." (PMID 32957307, 2020). "TMAO is also associated with C-reactive protein (CRP) and endothelial dysfunction in the setting of increased gut permeability and is related to increased serum levels of LPS endotoxin." (PMID 32169105, 2020). "Endothelial dysfunction is also correlated with markers of chronic (low-grade) inflammation, such as C-reactive protein (CRP) and cardiovascular risk predictors, such as adiponectin and brain natriuretic peptide (BNP)." (PMID 30621010, 2019). "We selected molecular markers that are associated with inflammation (including leukocytes, fibrinogen and C-reactive protein), associated with endothelial dysfunction (microalbuminuria), as well as associated with atrial dysfunction (NT-proBNP levels)." (PMID 31057479, 2019). "Similar to our study, a multi-ethnic cohort study showed that a Western type of dietary pattern rich in meat, processed meat, and sweets had a positive association with CRP levels, interleukin-6, and endothelial dysfunction." (PMID 31480674, 2019). "In a subsample of the Nurse’health Study, a Mediterranean diet index score was inversely associated with circulating CRP and IL-6, as well as markers of endothelial dysfunction (the adhesion molecules sICAM-1, sVCAM-1, and soluble E-selectin)." (PMID 30036988, 2018). "Higher trans-fatty acid consumption was associated with increased CRP levels and markers of endothelial dysfunction, whereas low-cholesterol/low-saturated fat diets and higher omega-3 fatty acid intake were correlated with reduced plasma CRP concentrations." (PMID 30274193, 2018). "In patients with acute coronary syndrome, CRP released in the coronary circulation has been found to cause endothelial dysfunction, possibly through dissociation of complex between CRP and lysophosphatidylcholine." (PMID 29644527, 2018). "It has been reported that CRP was independently associated with endothelial dysfunction in patients with RA, and proteinuria was associated with inflammation and endothelial dysfunction." (PMID 27537204, 2016). "UA is associated with metabolic abnormalities, increased C-reactive protein concentration and endothelial dysfunction, or even, to risk factors for cardiovascular diseases." (PMID 26441244, 2015). "Recently, a study in a rat model has shown that elevated CRP levels are associated with increased cardiovascular events and endothelial dysfunction." (PMID 26339132, 2015). "In HIV-negative patients, both leukocyte count and CRP and hsCRP have been linked to endothelial dysfunction and future CV events." (PMID 24958511, 2014).
endothelial dysfunction (continued). "To further address the role of systemic inflammation as a potential mediator of the link between periodontitis and endothelial dysfunction, we also evaluated the association between hs-CRP and FMD." (PMID 24386401, 2013). "There are recent reports associating an elevated C-Reactive Protein (CRP) with a microscopic endothelial dysfunction." (PMID 23864919, 2013). "Elevated C-reactive protein (CRP) levels caused by CS can also promote endothelial dysfunction by lowering the production of NO and reducing its bioactivity." (PMID 23316103, 2012). "CRP is also a well-known risk factor for vascular disease and endothelial dysfunction, both of which contribute to the rate and severity of cognitive decline over the lifespan." (PMID 22461977, 2012). "Abdominal obesity has been linked to elevated levels of CRP and is understood as a causative factor for endothelial dysfunction." (PMID 22461977, 2012). "The need for detection very low levels (< 3 mg/L) only became necessary when CRP was discovered to be a useful marker of endothelial dysfunction and future CVD risk." (PMID 29062730, 2012). "Elevated C-reactive protein (CRP) levels caused by TS promotes endothelial dysfunction by lowering the production of NO and diminishing its bioactivity, thereby limiting the smoker's ability to vasodilate via NO release." (PMID 21943155, 2011). "In conclusion, we report a reciprocal association between endothelial dysfunction and CRP levels in diabetic db/db mice." (PMID 20847810, 2010). "Moreover, regarding CRP, which is also associated with endothelial dysfunction, levels decreased during therapy in the MCS subgroups except in the VA-ECMO subgroup." (PMID 40002736, 2025). "Chronic activation of the immune system results in the production of proinflammatory cytokines, such as interleukin-6 (IL-6), tumor necrosis factor-alpha (TNF-α), and C-reactive protein (CRP), which are central to the inflammatory cascade associated with endothelial dysfunction and vascular damage." (PMID 40787484, 2025). "In addition, CRP not only serves as a biomarker for AS but also contributes to thrombosis risk by impairing endothelial function, promoting endothelial dysfunction, and inducing the release of circulating endothelial cells and endothelial microparticles." (PMID 40622923, 2025). "First, the association between migraine with aura, hs-CRP elevation, and endothelial dysfunction supports the hypothesis that vascular mechanisms play a key role in migraine pathogenesis." (PMID 41402545, 2025). "CRP and its mechanism of action are thought to be linked to endothelial dysfunction." (PMID 41281897, 2025). "Similarly, CRP and neutrophil activation have been linked to endothelial dysfunction and hypercoagulability, predisposing to vascular access failure." (PMID 41470152, 2025). "Elevated CRP levels have consistently been linked to increased mortality and adverse cardiovascular events, while lower albumin levels indicate poor nutritional and inflammatory status, endothelial dysfunction, and heightened oxidative stress." (PMID 41515507, 2025). "Elevated CRP levels are associated with increased CVD risk, and CRP itself may directly contribute to endothelial dysfunction and plaque instability." (PMID 40969606, 2025). "However, in this subgroup of patients we found that in the cases with CRP values > 0.8mg/dl, there was a 9-fold risk for the occurrence of endothelial dysfunction (LnRHI ≤ 0.51)." (PMID 39598310, 2024). "Notably, our study has shown a significant decrease in CRP levels, a systemic inflammatory mediator and an acute phase reactant that has been positively associated with cardiovascular disease risk and endothelial dysfunction." (PMID 38892688, 2024). "The CRP is a marker of systemic inflammation, and its elevation suggests an ongoing inflammatory response, leading to an increased risk of neuroinflammation, endothelial dysfunction, oxidative stress, and neuronal damage." (PMID 39596303, 2024).
endothelial dysfunction (continued). "CRP is associated with reduced endothelial vasoreactivity, and pharmacologic lowering of this marker could possibly reduce endothelial dysfunction, a process implicated in aneurysm development and rupture." (PMID 38893035, 2024). "LDL accumulation and oxidization may be associated with the degeneration of the aneurysm vessel wall, and CRP is associated with endothelial dysfunction." (PMID 38893035, 2024). "Thus, we suggest that CRP alone cannot fully induce the expression of endothelial dysfunction biomarkers, suggesting other risk factors of cardiovascular disorders are necessary to be involved in inducing endothelial dysfunction with CRP." (PMID 38627621, 2024). "In addition, higher TV viewing time in 7–10-year-old children has been associated with greater levels of CRP and of sVCAM-1, a biomarker of endothelial dysfunction." (PMID 36982042, 2023). "Furthermore, leptin is known to cause endothelial dysfunction by stimulating the production of C-reactive protein (CRP), cell adhesion molecules, and platelet tissue factor in endothelial cells." (PMID 37822930, 2023). "Moreover, low magnesium levels are implicated in endothelial dysfunction and inflammation, resulting in increased C-reactive protein (CRP) and cytokine secretion, increased nuclear factor kappa B (NF-κB), and platelet dysfunction, which can lead to thrombosis." (PMID 36837480, 2023). "In particular, elevated levels of CRP have been identified as a risk factor for vascular disease, and chronic exposure to inflammatory stimuli or injury can lead to oxidative stress, endothelial dysfunction, and intimal hyperplasia through an impact on nitric oxide bioavailability." (PMID 37570877, 2023). "The biological mechanisms underlying this association are thought to include mainly oxidative stress, systemic inflammation (e.g., interleukin-1β, tumor necrosis factor-α, interleukin-6, and C-reactive protein), and endothelial dysfunction caused by prolonged high SUA levels." (PMID 37004085, 2023). "First, PM2.5 is associated with biomarkers including systemic inflammation, thrombosis, and endothelial dysfunction, which are associated with elevated fibrinogen, C-reactive protein, white blood cell count, activation markers P-selectin, and soluble CD40 ligand." (PMID 35837365, 2022). "In addition, CRP causes endothelial dysfunction by inhibiting nitric oxide production, thereby preventing the normal function of vasodilatory responses that occur in response to increased pressures." (PMID 35929616, 2022). "This may be explained by the fact that SARS-CoV-2 causes endothelial dysfunction and increases coagulability, as evidenced by the increased levels of C-reactive protein and D-dimer observed in these patients." (PMID 32530389, 2020). "Increased CRP causes expression of adhesion molecules and plasminogen activator inhibitor-1 and diminishes nitric oxide production, resulting in vasoconstriction, pro-thrombotic, and pro-inflammatory statuses linked to endothelial dysfunction." (PMID 32549101, 2020). "CRP levels are known to be independent predictors of cardiovascular risk, and contribute directly to the genesis of atherosclerotic lesions, determining endothelial dysfunction, which is a marker of vascular damage and is a well-known feature of SLE." (PMID 31052336, 2019). "Inflammatory markers such as CRP and anti-inflammatory cytokines correlate with underlying causes and consequences of the inflamed uremic phenotype such as oxidative stress, endothelial dysfunction, CVD, infections and protein-energy malnutrition (PEM, also referred to as PEW)." (PMID 31027481, 2019). "Alternatively, alteration in glomerular hemodynamic derived from endothelial dysfunction might be responsible for the CRP-related increased risk for incidence of CKD." (PMID 27537204, 2016). "Smoking, FBG, HbA1C, Hcy and hs-CRP are significantly associated with endothelial dysfunction." (PMID 26150839, 2015).
endothelial dysfunction (continued). "Leptin, IL-6, and CRP via deduction of nitrite oxide affect the endothelial activities and this process causes vascular contraction, leucocytic adherence, platelets activation, oxidative stress, and thrombosis that will result in endothelial dysfunction." (PMID 25242867, 2014). "Previous studies showed that hyperglycemia and hyperlipidemia can cause endothelial dysfunction by affecting nitric oxide synthesis or degradation, which may increase hs-CRP levels." (PMID 24349092, 2013). "C-Reactive Protein is an important cardiovascular risk marker and several studies have attempted to demonstrate that this is an active molecule and relevance in the process of Endothelial Dysfunction." (PMID 23864919, 2013). "Also, C-reactive protein, the prototypic marker of inflammation and cardiovascular risk marker, has been shown to promote atherogenesis, and increased levels of C-reactive protein are associated with endothelial dysfunction." (PMID 24171112, 2013). "CRP may act not only as a marker of cardiovascular disease but may also have biological properties that cause endothelial dysfunction." (PMID 23717483, 2013). "Of the markers of chronic inflammation (CRP, and IL-6) and endothelial dysfunction (sICAM-1), sST2 showed a significant association after age-sex adjustment only with sICAM-1, with a relative increase of 4.9% (2.5% to 7.3%, p = 0.0001) per SD increase in log sST2." (PMID 23112853, 2012). "Elevated CRP and other inflammation biomarkers are associated with endothelial dysfunction and an increased risk of cardiovascular events; the effect of chronic immune activation on inflammation-related processes (e.g., coronary atherosclerosis) in these populations is an area for further research." (PMID 21477359, 2011). "Nevertheless, although CRP has shown consistency as a cardiovascular risk biomarker across large prospective studies, with relative risk ratios approaching those of classical cardiovascular risk factors, its contribution to the current evaluation model of endothelial dysfunction remains minor." (PMID 40529825, 2025). "Thus, CRP, in addition to being a marker of an inflammatory state, may directly cause endothelial dysfunction." (PMID 36830079, 2023). "Additionally, considering that CRP is a causative factor of endothelial dysfunction, which also has an important role in the pathogenesis and prognosis of CHF, this inflammatory biomarker can be used as a prognostic indicator of CHF patients with dilated cardiomyopathy." (PMID 34073616, 2021). "Thus, identification of elevated CRP as a risk marker for endothelial dysfunction may be useful to link a systemic marker of inflammation to progression of atherosclerotic disease and HF." (PMID 33804661, 2021). "In addition to the modifying effect of TFAs on the lipid profile, dietary intake of TFAs has been associated with an increase in markers of endothelial dysfunction such as CRP, interleukin-6, soluble tumor necrosis factor receptor 2, E-selectin and soluble cell adhesion molecules." (PMID 26920731, 2016). "Elevated levels of inflammatory mediators such as C-reactive protein, interleukin-6, and tumor necrosis factor-α contribute to endothelial dysfunction, promote lipid deposition, and accelerate atherogenesis." (PMID 41598548, 2026). "Periodontitis triggers systemic release of inflammatory mediators such as C-reactive protein, interleukin-6, and tumor necrosis factor-α, all of which are established contributors to endothelial dysfunction and atherosclerosis." (PMID 41598548, 2026). "Elevated CRP levels after PCI indicate an ongoing inflammatory response which can worsen endothelial dysfunction and lead to plaque instability." (PMID 41517773, 2026). "Clinical studies have linked periodontal disease to increased systemic levels of C-reactive protein (CRP), interleukin-6 (IL-6), and endothelial dysfunction, which are known contributors to cardiovascular morbidity." (PMID 40868899, 2025).
endothelial dysfunction (continued). "CRP, produced in the liver in response to IL-6, is not only a marker but also an active participant in endothelial dysfunction, promoting monocyte adhesion and plaque progression." (PMID 41007869, 2025). "High-sensitivity C-reactive protein (hs-CRP) is a well-established biomarker of systemic inflammation and endothelial dysfunction." (PMID 41402545, 2025). "Systemic inflammation serves as the key link between the two, with elevated biomarkers such as C-reactive protein and interleukin-6 observed in individuals with PD, driving endothelial dysfunction and atherogenesis." (PMID 40722588, 2025). "Chronic inflammation, marked by elevated cytokines (e.g., IL-6, TNF-α) and acute-phase reactants like CRP, accelerates endothelial dysfunction and plaque instability." (PMID 41202086, 2025). "ET-1 is a potent vasoconstrictor and marker of endothelial dysfunction, while CRP is released into circulation in response to inflammation and is a clinically relevant marker of cardiovascular disease risk." (PMID 40425613, 2025). "CRP, as an acute-phase protein, further exacerbates oxidative stress and endothelial dysfunction, ultimately contributing to organ damage and functional decline." (PMID 41229520, 2025). "Systemic inflammation marked by elevated levels of CRP, TNF-α, and IL-6 has been linked to increased vascular stiffness and endothelial dysfunction, which tend to elevate systolic pressure more than diastolic." (PMID 40584971, 2025). "CRP promotes endothelial dysfunction and accelerates the formation and progression of atherosclerotic plaques." (PMID 41010838, 2025). "In RA, endothelial dysfunction and cardiovascular death are correlated with C-reactive protein (CRP), a measure of systemic inflammation." (PMID 40937212, 2025). "Our findings extend beyond conventional biomarkers (e.g., CRP, D-dimer, and ferritin) by highlighting the pathophysiology-specific markers of endothelial dysfunction (MR-proADM), immune dysregulation (NLR), and lung injury (KL-6)." (PMID 40559088, 2025). "In addition, pro-inflammatory cytokines (e.g., IL-6 and c-reactive protein) may play a role in the relationship between depressive symptoms and lung function in older adults, causing endothelial dysfunction and reduced alveolar function, promoting the development of COPD." (PMID 40255497, 2025). "This relationship is exemplified by the Endothelial Activation and Stress Index, Ferritin, and CRP score, which provides a comprehensive measure of endothelial dysfunction and systemic inflammation." (PMID 40193078, 2025). "These compounds attenuate systemic inflammation by lowering circulating levels of C-reactive protein (CRP), interleukin-6 (IL-6), and tumor necrosis factor-α (TNF-α), biomarkers consistently associated with endothelial dysfunction." (PMID 41155474, 2025). "Collectively, these mechanistic insights support CRP as an active participant in DR pathogenesis, affecting endothelial dysfunction, cytokine signaling, oxidative injury, and VEGF-driven angiogenesis." (PMID 41159344, 2025). "C-reactive protein (CRP), a systemic inflammatory mediator whose levels are associated with endothelial dysfunction, is a causal factor of CAD and a predictor of evolution in CAD alike." (PMID 40283152, 2025). "Increased levels of prothrombin, thrombin, fibrinogen, sEPCR, and CRP pointed to persistent endothelial dysfunction and coagulation imbalance." (PMID 41181095, 2025). "This cascade stimulates the production of cytokines (e.g., IL-6, TNF-α), acute-phase proteins (e.g., CRP), and adhesion molecules, which collectively contribute to endothelial dysfunction and systemic inflammation." (PMID 40870942, 2025). "Markers of inflammation and endothelial dysfunction include C-reactive protein (CRP) and high-sensitivity CRP (hs-CRP)." (PMID 41406476, 2025). "Studies have demonstrated that the presence and severity of endothelial dysfunction correlate with inflammatory markers and mediators like C-reactive protein." (PMID 40099259, 2025).